EGFR (epidermal growth factor receptor)
Diseases named in the same sentence as EGFR in open-access papers (continued):
Sharing a sentence is not in itself a finding about the gene and the disease.
tumor (continued). "To confirm the anti-tumor effect, we examined the inhibitory effect of Formo on osimertinib sensitive cells, HCC827 (EGFR Del E746-A750), H3255 (EGFR L858R), and H1975 (EGFR L858R/T790M), and osimertinib resistant cells A549 (EGFR WT), H1299 (EGFR WT), and HCC827 OR (osimertinib acquired resistant)." (PMID 32276600, 2020). "Given that SIAH is the most conserved signaling module and the most downstream “gatekeeper” enzyme in the tumor-driving EGFR/HER2/RAS signaling pathway, SIAHON/OFF expression can serve as an ON/OFF binary code and an excellent biomarker for cellular proliferation in residual tumor cells post-NACT." (PMID 32542231, 2020). "Conversely, MMP14 expressed by NSCLC cancer cells and myeloid cells in the tumor microenvironment digests the heparin-binding EGF-like growth factor (HB-EGF) to generate both soluble and membrane-bound heparin-independent growth factors that can activate EGFR signaling." (PMID 33014869, 2020). "On the other hand, the activation of EGFR induces tyrosine phosphorylation of the cytoplasmic integrin β4 subunit through the Src family kinase Fyn, further downstream phosphoinositol-3-kinase (PI3K) and ERK are activated to foster cell migration and tumor invasion." (PMID 32796709, 2020). "There are evidences suggesting that EGFR-TKI may have an immunostimulatory effect by potentiating the induction of antigen presenting proteins in response to interferon-γ and enhancing T cells or NK cells mediated tumor killing." (PMID 32983977, 2020). "The notion that epithelial phenotype directly correlates with the efficacy of EGFR targeted therapies was put forward when early clinical trials performed in non-selected NSCLC patients identified a link between tumor E-cadherin levels and response to first generation EGFR TKI erlotinib." (PMID 32292420, 2020). "Therefore, EGFR‐specific immunotherapy should be administered locally into the tumor rather than as systemic/intravenous injections." (PMID 32592435, 2020). "EGFR T790M mutation was detected in 29 patients (23.4%) with a median variant frequency of 0.62% (range, 0.19–10.31%) using ICP analysis, but not in the TTG analysis of tumor tissue." (PMID 32823871, 2020). "The sEGFR level was not related to tumor EGFR expression (4.2 for ≤ 10% versus 4.2 ng/mL > 10% EGFR staining, P = 0.8), [89Zr]Zr-cetuximab blood concentration on PET, or %ID in the liver (a potential “sink” organ for cetuximab-sEGFR complexes; P = 0.33 and P = 0.62 respectively)." (PMID 31705176, 2020). "In addition, the reactions to hypoxic tumor environment between EGFR and CA9 are contrary, which may contribute to the tumor progression." (PMID 32365566, 2020). "First, regarding EGFR expression on the ocular surface, changes in benign diseases and age-related changes in normal tissues may not have been sufficiently investigated." (PMID 32833992, 2020). "Furthermore, radioiodine cross-linking anti-EGFR (cetuximab) and bovine serum albumin (BSA) polycaprolactone (PCL) nanoparticles were also useful to induce tumor regression, which in turn enhanced the cytotoxicity on tumor cells and limited the adverse effects of chemical agents." (PMID 33321953, 2020). "Therefore, in order to achieve high tumor uptake and low nonspecific binding, structural modifications need to be made that decrease lipophilicity without reducing affinity toward EGFR L858R/T790M." (PMID 32599930, 2020). "Since the patient data is for the proportions of biopsies containing EGFR and PDGFRA amplified cells above a given density threshold, which we chose to be 10% of the tissue sample, we define an equivalent measure for each simulated tumour by integrating solutions across the whole tissue domain." (PMID 33120534, 2020). "Interestingly, P-EGF-Cy7 did not exhibit any significant tumor accumulation, while in vitro results showed a relatively strong interaction with EGFR." (PMID 31906300, 2020).
tumor (continued). "The target specificity of Anti-EGFR-Nanobody toward A549 cells and possible EPR effect of Nb@IC-NPs could play a critical role in the enrichment of O2 level and IR-1048-MZ contrast agent at the tumor site after the administration of Nb@IC-NPs." (PMID 33292202, 2020). "In addition, gefitinib reduced the p‐EGFR level in tumor tissue, and this effect was not reversed by 3‐MA treatment." (PMID 31823521, 2020). "Moreover, EGFR promotes tumor progression and therapeutic resistance independent of its kinase activity." (PMID 32694521, 2020). "Regulation within the tumor microenvironment includes activation of receptor tyrosine kinases such as the vascular endothelial growth factor receptor (VEGFR), epidermal growth factor receptor (EGFR), fibroblast growth factor receptor (FGFR), and platelet-derived growth factor receptors (PDGFR)." (PMID 32280512, 2020). "Additionally, some evidence suggests that tumour-derived EVs containing EGFR and EREG may also promote tumour angiogenesis." (PMID 33143170, 2020). "However, high background staining was observed in tumor-negative tissues for EGFR, VEGF-A and L1CAM." (PMID 32545676, 2020). "There was a significant difference in smoking status and Ki-67 expression levels between the EGFR wild-type group and the EGFR mutant group, while sex, age, pathological grade, histological type, tumour stage, and tumour diameter were not significantly different." (PMID 32103127, 2020). "The positive rate of EGFR mutation identification was 76% with cobas, although EGFR mutation-negative patients retained responses to TKI therapy equivalent to positive patients did; however, the tumour content ratio of negative samples was significantly lower than that of positive samples." (PMID 32028905, 2020). "In this setting, there is a negative correlation between miR-615-5p and EGFR, so the overexpression of miR-615-5p induces the repression of EGFR and its downstream effects on growth, proliferation, invasion and migration of the tumor cells." (PMID 32605009, 2020). "The present study demonstrated that the activated EGFR‐CAR NK cells upregulated cytokine secretion, promoted cytotoxicity against the TNBC cells exhibiting upregulated EGFR expression in vitro, and inhibited tumor growth in mice without affecting mice bodyweight." (PMID 32592435, 2020). "Moreover, antitumor potency of EGCG was also shown to result from its ability to suppress growth factor receptors such as epidermal growth factor receptor (EGFR) and insulin-like growth factor receptor (IGF-1R) that play significant roles in tumor survival and growth." (PMID 33167519, 2020). "The activated EGFR is known to regulate LOX expression via the PI3K/AKT, MEK/ERK and SAPK/JNK pathways, as observed in human non-small cell lung carcinoma cell lines and confirmed in vivo in an orthotopic metastasis mouse model and in human tumor tissue microarray analysis." (PMID 32708046, 2020). "In addition, molecular tumor characteristics (e.g., IDH status, EGFR amplification, and other molecular characteristics) may be represented in TEP-spliced RNA profiles and deserve further investigation." (PMID 33103128, 2020). "Patient 3’s tumour exhibited the least response to radiotherapy as assessed by changes in volume and the patient expired from disseminated relapse at 3 months following treatment, without accessing EGFR-targeted therapy due to poor fitness." (PMID 32471446, 2020). "This explained well the high EGFR protein levels observed under hypoxia as compared to the moderate mRNA levels, in particular, in the DTC cell line BC-M1, suggesting that this mechanism might be of potential relevance in tumor cell dissemination." (PMID 32466213, 2020).
tumor (continued). "Immunohistochemistry of the proliferation marker Ki67, epidermal growth factor receptor (EGFR) and fibronectin and a TUNEL-assay were performed to analyze the effect of CAFs on both tumor cell proliferation and response to cisplatin and cetuximab treatment in tumor spheroids (3D)." (PMID 33353547, 2020). "SOX2 suppression by RNAi or abrogation of EGFR, Src, or Akt signaling through EGFR tyrosine kinase inhibitors Gefitinib, Erlotinib, or BIBW2992 or Src inhibitor Dasatinib could result in curbing stem-like properties and regrowth of tumor." (PMID 30517668, 2020). "Of note, GOLM1, another protein of the Golgi apparatus that is overexpressed in some types of tumor cells, regulates EGFR recycling without affecting its glycosylation, suggesting that GOLPH3 could also directly affect EGFR recycling." (PMID 33238647, 2020). "Notably, the model-estimated kkill for MIA PaCa-2 tumours was two-fold higher than that of PANC-1, consistent with the observation that CTX-MMAE was more efficacious in the MIA PaCa-2 xenograft tumour, despite the higher EGFR density on PANC-1." (PMID 32913288, 2020). "In addition, our study finds that LXR-α is regulated by the EGFR/AKT/FOXO3A axis and a combination of EGFR inhibitor Afatinib and GW3965 simultaneously increases and activates LXR-α, resulting in an increase of tumor suppressors and, ultimately, tumor inhibition." (PMID 33224867, 2020). "However, TG mice were more resistant to DEN-induced hapatocarcinogenesis at 6, 10, and 12 months of age, showing delayed hepatocyte proliferation and apoptosis, lower tumor incidence, smaller size and fewer number, compared with age-matched WTs, partially through downregulation of MET and EGFR." (PMID 32489479, 2020). "In contrast to tissue-based biopsy sampling of a single lesion, ctDNA-based assays can enable real-time detection of tumour heterogeneity as it evolves as well as the identification of alterations in RAS and the ECD of EGFR that might coexist after anti-EGFR therapy." (PMID 32632268, 2020). "Despite numerous efforts to target epidermal growth factor receptor (EGFR), commonly dysregulated in GBM, approaches directed against EGFR have not achieved the same degree of success as seen in other tumor types, particularly as compared to non-small cell lung cancer (NSCLC)." (PMID 33187135, 2020). "EGFR mutant mice fed with doxycycline food for 30 days and receiving vehicle liposomes presented a dramatic increase in tumor burden compared with control animals which did not express mutant EGFR, shown by increased lung weight, increased number of nuclei/mm2 or micro‐CT scan of the entire lung." (PMID 32125091, 2020). "We also described the interaction between EGFR and HBEGF: the feedback loop between these 2 genes regulates astrocytes' maturation and promotes gliomagenesis in specific contexts; the silencing of 1 of the partners tends to reduce tumor growth and increases survival in vivo." (PMID 33155039, 2020). "The presence of a group of GB-IDHwt without alterations in EGFR may explain part of the absence of effect of RTK inhibitors in this type of tumor." (PMID 33172155, 2020). "EGFR amplification was not seen in any tumor sample, consistent with other studies." (PMID 33023139, 2020). "Importantly, there were no EGFR alterations found in liquid that were not present in tumor tissue in newly diagnosed patients, leading to an NPA of 100%." (PMID 32596507, 2020). "It indicated that EGFR might not constitute the major clone of the tumor, and rather the subclone which was missed out by needle biopsy." (PMID 32505185, 2020).
tumor (continued). "Two parallel signalling pathways downstream of EGFR, including MEK1/2–ERK1/2 and MEK5–ERK5, phosphorylate and activate the inducible RSK3 protein, eventually leading to the enrichment of activated RSK3 protein in tumour cells to counteract the acute killing effect of JQ1." (PMID 31937753, 2020). "Targeting angiogenesis or EGFR alone does not yield adequate tumor control in most solid tumors." (PMID 32337094, 2020). "However, there is no thoroughly established EGFR+ mouse tumor model, and commercially available anti-mouse EGFR Abs are too expensive for experimental cancer therapy studies." (PMID 32927646, 2020). "EGFR amplification and PTEN deletion were more prevalent in TCGA (49.6%/35.6%, respectively) compared to IRCR cohort (32%/26.3%), suggesting that IRCR tumors may undergo alternative molecular pathways during tumor propagation." (PMID 32794373, 2020). "As such, identification of EGFR mutation status is crucial for TKI treatment to be effective; however, the molecular test for EGFR mutation status sometimes cannot be performed when a tumor sample is not available." (PMID 33134170, 2020). "Overexpression of EGFR has also been thought to be associated with the development of acquired resistance, but one study showed that cetuximab combined with chemotherapy improved relapse/metastatic HNSCC and KRAS wild-type mCRC regardless of tumor EGFR expression levels." (PMID 32793499, 2020). "Because of its ability to bind EGFR, nimotuzumab can competitively interfere with the binding of EGF to EGFR, resulting in the blockade of downstream signaling pathways, inhibiting tumor cell proliferation, promoting tumor cell apoptosis, and enhancing the efficacy of radio- and/or chemotherapy." (PMID 32850421, 2020). "Furthermore, EGFR-targeting lipo-polyplexes click-modified with GE11 were applied for EG5 siRNA/pretubulysin (PT) co-delivery; significant combination effects were confirmed in EGFR positive tumor cell cultures." (PMID 32961908, 2020). "Previously, we demonstrated that activation of EGFR/Ras led to the downregulation of the homoeostatic chemokine CCL27 in transformed keratinocytes, resulting in significantly impaired recruitment of tumour-targeting leukocytes, leading to evasion from tumour-immune surveillance." (PMID 32601464, 2020). "The resulting rAAV transduced EGFR overexpressing tumor cells but not a control cell line." (PMID 33333826, 2020). "No EGFR protein overexpression was noted in the other tumours (data not shown)." (PMID 32058674, 2020). "This could be because EGFR-positive cases were classified into three categories (1+, 2+ and 3+), rather than being measured as the percentage of positive tumor cells, as we have done in the present study." (PMID 32170146, 2020). "On the other hand, patients with EGFR-TKI sensitive NSCLC might rather benefit from combinatorial treatment with anti-CTLA-4 antibody, since anti-PD-L1 antibodies can only be efficient in tumor cells with high PD-L1 expression." (PMID 32486375, 2020). "Therefore, upfront EGFR-TKI alone without local RT has been used with the advantage of avoiding radiation-induced neurotoxicity until tumour progression." (PMID 32298306, 2020). "For example, EGFR activation increases pyruvate kinase isozymes M2 (PKM2) expression by activating protein kinase C epsilon type/nuclear factor kappa-light-chain-enhancer of activated B cells (PKCε/NF-κB) signaling pathway, which therefore promotes glycolysis and subsequent tumor cell proliferation." (PMID 30824700, 2019).
tumor (continued). "EGFR isoforms II-IV are soluble proteins that do not mark the expressing cell itself, but rather diffuse in the extracellular space, probably bind to surrounding non-tumor cells, and possibly mislead the immune system." (PMID 31438847, 2019). "Similarly, in two other studies, cetuximab (an anti-EGFR antibody)-conjugated NP loaded with paclitaxel or gemcitabine was also found to show superior efficacy and tumor-targeting effects compared to NP without antibody conjugation." (PMID 30791634, 2019). "In middle stage LADC, receptor EGFR can be activated by interacting with ligands EGF, which may be secreted by nearby macrophage stimulated by hypoxia, and BGN, which may be secreted by tumor endothelial cells." (PMID 31217907, 2019). "In one study evaluating the combination of erlotinib plus nivolumab, durable tumor regression in both treatment (TKI or chemotherapy) naïve and TKI-treated patients was reported and there are several additional trials evaluating the efficacy of combining PD-1/PD-L1 inhibitors with EGFR TKIs." (PMID 31291990, 2019). "However, EGFR inhibition in HCC does not impair tumor progression as the significant level of acute tumor cell death associated with EGFR inhibition induces compensatory proliferation and fosters tumor evolution." (PMID 31015417, 2019). "Our data showing no radiosensitivity differences between EGFR mutant and wild-type groups at high doses (i.e., SF8 and SF6) suggest that hypofractionated irradiation employing high fraction size is likely to achieve comparable tumor control regardless of EGFR status." (PMID 31349558, 2019). "Importantly, organoids grown from surrounding normal tissues showed lower EGFR expression levels than their tumor counterparts, and were not affected by the treatment." (PMID 31694307, 2019). "Similarly, the EGFR inhibitor erlotinib, but not dasatinib, was found to significantly reduce tumor size in a randomized trial with operable HNSCC patients." (PMID 31731442, 2019). "Monoclonal antibodies directed against the epidermal growth factor receptor (EGFR) clearly revolutionized metastatic CRC (mCRC) treatment, improving clinical response and survival rate, as well as disease control, in addition to tailoring CRC therapy based on tumor molecular characterization." (PMID 31717544, 2019). "However, the responses are not durable, and the magnitude of tumor regression is variable, suggesting the existence of genetic modifiers of EGFR dependency." (PMID 31741433, 2019). "Activation of EGFR stimulates several downstream signaling cascades, including the RAS/ RAF/MAPK, PI3K/Akt/mTOR, JAK/Src/STAT, and phospholipase C gamma/protein kinase C pathways, triggering oncogene transcription and promoting tumor proliferation, survival, invasion, and drug-resistance." (PMID 31422383, 2019). "Similarly to the luciferase assay results, using flow cytometry we noted essentially no reduction for EGFR-mediated transduction efficiency with the ΔRGD mutant in comparison to the virus with the RGD motif in tumor cells from 2D fibroblast-tumor co-cultures." (PMID 31811202, 2019). "Upstream amplification of growth factor receptors and substrates, such as epidermal growth factor receptor (EGFR), insulin-like growth factor receptor and insulin receptor substrate (IRS), promotes the PI3K and MAPK pathways, which cross-talk with mTORC1, and thus enhance tumour-promoting processes." (PMID 35582282, 2019). "Another possible explanation is that few of the injected probes could reach EGFR-expressing tumor cells because the large part of the injected volume would percolate out of the injection site via vascular flow without accessing tumor cells." (PMID 30669481, 2019).